LEP (leptin)
Diseases named in the same sentence as LEP in open-access papers (continued):
Sharing a sentence is not in itself a finding about the gene and the disease.
Obesity (continued). "Leptin-resistant diet-induced obesity (DIO) rats demonstrated decreased CCK sensitivity on vagal afferent nerves, which attenuates the effect of CCK on satiety." (PMID 36834794, 2023). "For example, obesity-mediated hypertrophy of adipose tissue stimulates the secretion of leptin, resistin, and pro-inflammatory cytokines, which can induce ER stress, inflammation, and metabolic abnormalities in the liver." (PMID 37229466, 2023). "Further, a stepwise significant increase in leptin, insulin, serum glucose and a decrease in ghrelin was found in stage I and II obesity participants when compared with OW and LS." (PMID 38313840, 2023). "In people with obesity, the level of leptin in the blood is almost 10 times higher than in people with a normal body weight." (PMID 36981858, 2023). "The leptin/adiponectin ratio (L/A ratio) is a better indicator of metabolic diseases, such as obesity and diabetes mellitus." (PMID 36829148, 2023). "The examination of fat tissue in individuals with obesity showed that more adipocytes produce leptin." (PMID 37512149, 2023). "Collectively, these results unravel what we believe to be a previously unrecognized hypothalamic neuronal Slug/epigenetic reprogramming/leptin resistance axis that promotes energy imbalance, obesity, and metabolic disease." (PMID 36512408, 2023). "Its anti-obesity properties are due to its capacity to attenuate leptin resistance and the subsequent amelioration of glucose deprivation-induced leptin resistance, which is involved in the pathophysiology of obesity." (PMID 36986440, 2023). "As a member of adipokines, leptin can act as a proinflammatory cytokine and play some role in the development of obesity and insulin resistance." (PMID 37114144, 2023). "The commonly used Zucker Diabetic Fatty (ZDF) rat as well as the ob/ob and db/db mouse models have genetic defects in the leptin signaling pathway, inducing obesity and insulin resistance, which are uncommon in human T2D development." (PMID 37233701, 2023). "Obesity in children promotes hypertension through adipokines such as leptin, increasing sympathetic nervous system (SNS) activity." (PMID 37509481, 2023). "ER stress is also implicated in leptin resistance, and activation of the UPR can block the leptin signaling network and contribute to energy imbalances in obesity and related diseases." (PMID 37138269, 2023). "The same study also showed a significant reduction in leptin concomitant to an increase in adiponectin; this is partly because of the direct relationship between adipocytes in obesity and its influence on leptin levels." (PMID 37090773, 2023). "Obesity exerts a multitude of effects both locally and systematically, through a series of inflammatory mediators (increased leptin, reduced adiponectin, TNF-α, IL-6), growth factors (insulin, IGF-1), and metabolism molecules (visfatin, grehlin, and resistin)." (PMID 37834153, 2023). "Taken together, our results show that WKYMVm ameliorates obesity by improving lipid metabolism and leptin signalling, suggesting that WKYMVm can be a useful molecule for the development of anti‐obesity agents." (PMID 37603580, 2023). "Obesity is related to an increased production of cytokines for the pro-inflammatory response (e.g., leptin, TNF-α, and IL-6) and a decreased secretion of adipokines that protect inflammatory response (e.g., adiponectin and IL-10)." (PMID 37821991, 2023). "This can contribute to the explanation of how there is a compensatory upregulation of leptin in obesity that then results in leptin resistance." (PMID 38255639, 2023). "Our results demonstrated that this rat genetic model of obesity with leptin and insulin resistance is stable even at 10 months of age and is therefore suitable for long-term studies." (PMID 37110210, 2023). "Studies have demonstrated that insulin and leptin resistance observed in individuals with obesity can alter the prefrontal function as well as the cognitive function that regulates food intake." (PMID 37261609, 2023).
Obesity (continued). "We aimed to investigate the metabolic state and leptin level among patients with obesity and type 2 diabetes mellitus, and the effect of empagliflozin upon these parameters." (PMID 36901837, 2023). "In particular, levels of leptin are generally increased in subjects with obesity, because of the obesity-induced leptin resistance, which is thought to worsen IR." (PMID 36980074, 2023). "Leptin controls satiety, and adiponectin regulates insulin sensitivity, and both have been studied in depth related to obesity." (PMID 37492183, 2023). "Other causes of monogenic obesity, such as POMC (proopiomelanocortin) gene mutations or leptin gene mutations, are much rarer." (PMID 37629396, 2023). "Adipokines, such as leptin and adiponectin, are an essential link between metabolism and immune function, but are dysregulated in obesity, contributing to low-grade inflammation." (PMID 37463992, 2023). "A decrease in leptin levels and leptin resistance are considered the main contributing factors to obesity by inducing a hyperphagic phenotype and nutrient overload." (PMID 38001815, 2023). "In obesity, an increased concentration of leptin is due to the excessive level of adipocytes that impairs the leptin signaling receptor, developing a condition known as leptin resistance." (PMID 37237937, 2023). "A large body of results from humans and animal studies indicated that elevated leptin levels were observed in obese hosts, especially in diet-induced obesity." (PMID 37114144, 2023). "In the literature, there are significant links between the leptin hormone, a product of the obesity gene, and the development of ovarian cancer." (PMID 37155466, 2023). "It has been proven that the high-fructose diet increases blood triglyceride levels, which suggests its possible influence on the induction of leptin resistance and, thus, overweight and obesity." (PMID 36834291, 2023). "In conclusion, the development of obesity is a complex interplay between leptin, the autonomic nervous system and CNS, adipose tissue, and insulin-resistance." (PMID 37795371, 2023). "Still according to our previous study, in CD4+ T cell cultures from lean AA patients, obesity-related leptin concentration enhanced Th2- and Th17-related cytokine production and impaired Treg function in response to polyclonal activators." (PMID 37954580, 2023). "OT has been suggested to interact with leptin in order to appropriately regulate appetite and body weight because the administration of leptin has previously been shown to activate hypothalamic OT neurons in normal and diet-induced obesity rats." (PMID 37375670, 2023). "With respect to histone modifications, inhibitors of his-tone deacetylase 6 are effective leptin sensitizers and anti-obesity agents in diet-induced obese mice." (PMID 36674935, 2023). "Leptin, a peptide hormone secreted by adipocytes, has also been suggested as a possible link between obesity and mood disorder." (PMID 38260805, 2023). "Subjects with obesity showed an altered serum cytokine profile, characterized by increased levels of leptin, FGF21 and NOV/CCN3, a decreased level of adiponectin, and similar levels of vaspin and chemerin compared to normal-weight subjects." (PMID 38137540, 2023). "Most recently, the specific deletion of both REV-ERBs in the tuberal hypothalamic nuclei (including the ARC, VMH, and DMH) revealed the crucial role of REV-ERB in hypothalamic control of food intake and diurnal leptin sensitivity in diet-induced obesity." (PMID 36670468, 2023). "Among adipokines, leptin levels were shown to be directly proportional to obesity and body fat levels, while its counter-hormone adiponectin resulted reduced." (PMID 37358728, 2023). "Leptin is a cytokine: what are the roles of LepR in microglia or astroglia to aid and abet obesity-induced hypothalamic inflammation?" (PMID 36769012, 2023).
Obesity (continued). "Obesity induces various metabolic dysfunctions and inflammatory processes that increase insulin, insulin-like growth factor, leptin, and interleukin-6, while decreasing adiponectin." (PMID 38013342, 2023). "Alternatively, it is possible that, through mechanisms requiring more research, hypothalamic neurons become resistant to leptin before the development of obesity." (PMID 37899888, 2023). "Collectively, these results suggest that Slug epigenetically suppressed LepRb expression, contributing to leptin resistance and obesity." (PMID 36512408, 2023). "During obesity, adipose tissue also secretes angiopoietin-like protein 2 or leptin, leading to increased inflammation and the development of cardiovascular diseases." (PMID 36614227, 2023). "In the most prevalent forms of obesity, particularly lifestyle-related cases in which overeating and a sedentary lifestyle are culprits, an insensitivity to spontaneous hyperleptinemia or leptin therapy presents as “leptin resistance”." (PMID 37047811, 2023). "Given the close relationship between obesity, leptin, and insulin resistance, there are various recommendations for the treatment of these conditions with the aim of reducing cardiovascular risk and diabetes mellitus, as well as improving asthma symptoms." (PMID 37629427, 2023). "Previous studies on breast cancer patients that demonstrated high serum leptin levels in breast cancer also showed a positive correlation between obesity and breast cancer." (PMID 37378223, 2023). "More direct and convincing evidence is needed to determine the contribution of leptin to the impaired function of MSC in the later stages of obesity." (PMID 36750692, 2023). "Since early-onset obesity produces chronic hyperleptinemia, we used SL-HFD rats to test if the elevation of endogenous leptin levels linked to obesity also increases NE content in mWAT, the ovaries, and the liver." (PMID 38069231, 2023). "So, physical exercise, diet alteration, weight reduction, adiponectin, and leptin supplementation should be carried out to protect against obesity-induced cognitive decline." (PMID 37363537, 2023). "Our research aimed to investigate the role of leptin/obR signaling in a female obesity-related neutrophilic airway inflammation murine model to provide possibilities for the development of drugs for obesity-related asthma." (PMID 37488474, 2023). "Leptin, the 167 amino acid product of the human gene for obesity, is involved in glucose and insulin signaling pathways through various mechanisms." (PMID 37375800, 2023). "For instance, leptin and adiponectin contribute to body weight regulation, while TNF-α, IL-6, and IL-1β are associated with local inflammation resulting from obesity." (PMID 37408757, 2023). "Increased circulating leptin, which characterizes obesity, was correlated with decreased circulating OPG." (PMID 37208545, 2023). "In contrast to leptin, individuals with obesity, type 2 diabetes (T2D), and metabolic syndrome have decreased adiponectin levels." (PMID 38001998, 2023). "Given the proven efficacy of cyanoenone-bearing semisynthetic triterpenoids in inhibiting the growth of neuroblastoma and preventing obesity in vivo, the effect of soloxolone methyl (SM) on leptin-stimulated Neuro2a cells was further investigated." (PMID 37895840, 2023). "Further studies are needed to explore the mechanism through which THC, via adipose adaptation and/or leptin sensitivity, reduces obesity-induced hepatic steatosis." (PMID 37762099, 2023). "This dysregulation in hypothalamic leptin signaling subsequently leads to overconsumption of nutrients and increased total body mass, thus aggravating obesity." (PMID 37795371, 2023). "Adiponectin is involved in the lowering of blood glucose and lipids, preserving insulin to remain sensitive, as well as expressed highly in the oxidation of fatty acid, while leptin takes part in abnormal conditions such as obesity and insulin resistance." (PMID 37175792, 2023).
Obesity (continued). "Leptin is another of the most studied adipokines due to its relationship to obesity and cardiovascular events." (PMID 37238961, 2023). "Thus, our results indicated that neutrophilic airway inflammation was significantly increased in the LPS/OVA + OVA-treated female obese murine model, and the leptin/obR axis may be associated with the pathogenesis of obesity-related neutrophilic airway inflammation in females." (PMID 37488474, 2023). "Upregulation of Cdc42 in obesity contributes to the development of insulin resistance through increased leptin production by hypertrophied adipocytes." (PMID 38068822, 2023). "Among the large set of genes influencing obesity, those in the leptin-melanocortin satiety signaling pathway are the most determinant known to date, with homozygous mutations in some causing early onset severe obesity with hyperphagia." (PMID 38174068, 2023). "Although the melanocortin system is a primary focus for leptin’s anorexigenic action in the hypothalamus, obesity in POMC LepRb −/− mice is only a fraction of that observed after global LepRb depletion." (PMID 37064917, 2023). "To date, resistance (leptin) or side-effects (melanocortins) prevented the development of anti-obesity medication." (PMID 37240340, 2023). "Leptin has a direct relationship with obesity, their levels are comparatively higher than those shown in subjects with a low fat content." (PMID 38015889, 2023). "In children with obesity or overweight, the adiponectin levels are significantly lower compared to those in normal-weight children, while the leptin levels are increased." (PMID 37763090, 2023). "Namely, there is dysregulation of ghrelin and leptin levels in obesity, both of which dampen central olfactory system function." (PMID 37960191, 2023). "One such adipokine is leptin, which is secreted in proportion to adipose tissue mass and is therefore increased in the setting of obesity and decreased in undernutrition." (PMID 37276236, 2023). "Intriguingly, overexpression of HDAC5 in the hypothalamus protects mice from diet-induced obesity by enhancing leptin-stimulated STAT3 phosphorylation, which subsequently elevates Pomc expression and inhibits food intake." (PMID 38027481, 2023). "The complete absence of leptin results in severe hyperphagia, decreased metabolic rate, and rapidly developing obesity, which can be reversed with the subsequent administration of leptin." (PMID 37047811, 2023). "Echoing this claim, obesity-related cytokines such as leptin and adiponectin are increasingly recognized as promising candidates in the development of breast cancer." (PMID 37274250, 2023). "Potential interventions targeting Cdc42 activity hold promise for reducing obesity and enhancing leptin sensitivity." (PMID 38068822, 2023). "Leptin resistance as a consequence of obesity is a mechanism for decreasing sensitivity to leptin actions." (PMID 37372025, 2023). "In conclusion, the present study provides the first evidence that low and high doses of supplemented Zn attenuate obesity-related central leptin resistance and cognitive decline." (PMID 36977735, 2023). "In this study, LEP expression was found to be upregulated in PCOS patients with obesity and in GCs treated with insulin." (PMID 37562217, 2023). "Collectively, our study showed that obR-b is the critical receptor that participates in leptin/obR-mediated M1 macrophage polarization and obesity-related neutrophilic airway inflammation in females." (PMID 37488474, 2023). "This is influenced by factors such as blood–brain barrier permeability, which results in leptin failing to suppress appetite and consequently leads to circulating hyperleptinemia amongst patients with obesity." (PMID 37878001, 2023). "When examining the relationship between genetics and obesity, an adipocyte-secreted protein known as leptin plays a role in nutrient homeostasis and satiety; it is also known as the "satiety hormone" as it helps to signal to the brain that the body is full." (PMID 37937009, 2023).
Obesity (continued). "The reduction of ZIP14 in obese patients negatively correlated with both leptinemia and adipose tissue leptin levels in obesity, as in ZIP14 knockout mice, which exhibited higher levels of leptin." (PMID 38260166, 2023). "The abundance of different obesity related proteins such as LEP, ITGAL, IKBIP, H2-AA, TAP2 and FABP5 was very low in AdEVs from lean mice and was detected in only one or no biological replicate." (PMID 36759608, 2023). "Pathogenesis involved in the development of fructose-induced obesity includes the following potential mechanisms: 1) leptin resistance, 2) true hyperphagia, 3) positive energy balance, and 4) increased body weight." (PMID 36751236, 2023). "Leptin and Adiponectin are two important adipose-regulatory factors in obesity, regulating sugar, fat, and energy metabolism." (PMID 36998473, 2023). "In people with obesity, there is often a condition called leptin resistance, in which the body becomes less responsive to the effects of leptin." (PMID 37600709, 2023). "A positive relationship exists between serum leptin levels and the percentage of body fat, as leptin is overproduced in those with obesity." (PMID 37049602, 2023). "Studies have also described increased adiposity and expression of obesity-related genes as well as increased placental leptin synthesis and leptin concentration in the cord-blood of offspring prematurely born to preeclamptic mothers." (PMID 37238374, 2023). "Early puberty development is marked by a simultaneous rise in body fat, and obesity can promote leptin secretion, which acts on the HPG axis, increases LH pulse rate and levels, and accelerates the initiation of puberty." (PMID 38317710, 2023). "The aim of this study was to evaluate the effect of leptin on reactive oxygen species’ (ROS) generation of smooth muscle cells (SMCs) from a rat model of obesity and hyperleptinemia." (PMID 36978976, 2023). "Highly infrequent single gene mutations (such as LEP, LEPR and POMC) stand for rare cases of monogenic obesity; however, some of them are also related to polygenic obesity (such as MC4R and FTO)." (PMID 36980866, 2023). "Taken together, these results demonstrate that LepRb+ neuron–intrinsic Slug cell-autonomously suppresses leptin signaling to induce leptin resistance, which leads to obesity." (PMID 36512408, 2023). "Similar to leptin, adiponectin has an effect on metabolic disorders such as insulin resistance, type 2 diabetes, and obesity." (PMID 37174950, 2023). "In obesity, excessive adipose tissue correlates with an increase in leptin levels and a decrease in adiponectin levels, while leptin gains pro-inflammatory properties." (PMID 37686525, 2023). "It is noteworthy to mention that some drugs used to sensitize tissues to leptin and affect obesity can modulate Cdc42 activity." (PMID 38068822, 2023). "These heterogeneous studies suggest that PVAT-derived leptin, under normal physiological conditions or during the early phase of obesity development, acts as a PDRF." (PMID 37190105, 2023). "Leptin regulated fat mass and body weight by suppressing food intake and stimulating energy expenditure, and numerous adult studies have shown that leptin is a biomarker for obesity, IR and MetS." (PMID 37274813, 2023). "For this reason, approaches to induce a partial decrease in circulating leptin and simultaneous increase in leptin sensitivity are being studied to replace other treatments for obesity with adverse effects." (PMID 37603580, 2023). "Patients with obesity exhibit higher plasma levels of leptin (average rate of 36 ng/mL) than those measured in normo-weight subjects (8 ng/mL)." (PMID 38136564, 2023). "In the obesity model, adipocyte hypertrophy occurred before hyperplasia, with increased secretion of leptin, ceramide, and vaspin and decreased secretion of adiponectin and omentin in hypertrophied adipocytes." (PMID 37645520, 2023).